ALB (albumin)
Diseases named in the same sentence as ALB in open-access papers (continued):
Sharing a sentence is not in itself a finding about the gene and the disease.
Hypoalbuminemia (continued). "In a randomized crossover study, patients with hypoalbuminemia undergoing intermittent hemodialysis experienced significantly fewer episodes of hypotension and better fluid removal when receiving albumin than when receiving saline." (PMID 39336939, 2024). "For women with hypoalbuminemia and lymphopenia, pre-chemotherapy nutrition support with monitoring of albumin and lymphocyte levels is warranted." (PMID 38400912, 2024). "Hypoalbuminemia, defined as serum albumin ≤ 3.5 g/dL, is often observed in chronically ill patients." (PMID 38972926, 2024). "At baseline determination, TAC in group 1 was 7.35 ng/mL and 21.95 ng/mL in group 2, with no significant distinction observed between genetic and biochemical parameters (creatinine serum, hematocrit, serum albumin, hypoalbuminemia)." (PMID 38674430, 2024). "Low albumin levels are a strong predictor of poor prognosis in HF patients, with persistent inflammation contributing significantly to hypoalbuminemia." (PMID 39659906, 2024). "This study offers evidence that in an ostensibly healthy general adult population, individuals with hypoalbuminemia (defined as serum albumin levels ≤35 g/L) experienced a higher mortality rate." (PMID 39010980, 2024). "The frequency and severity of hypoalbuminemia in the two groups was similar in the consolidation phase, but during maintenance chemotherapy the latter group had less frequent and severe albumin suppression." (PMID 39305296, 2024). "It is noteworthy that the prevalence of hypoalbuminemia (serum albumin ≤35 g/L) was higher among individuals aged 65 years or older (118/3306, 3.6%) compared to those under 65 years of age (288/14,624, 1.0%; P < 0.0001)." (PMID 39010980, 2024). "Research has demonstrated that elevated levels of UA can stimulate the release of inflammatory cytokines such as interleukin-6 and tumor necrosis factor-alpha, which in turn inhibit albumin synthesis, leading to hypoalbuminemia." (PMID 39659906, 2024). "Previously, we showed that FC 5 and/or 10 mg/kg/day i.p. for 30 days caused anemia, lymphocytopenia, neutrophilia, hypoalbuminemia, hepatomegaly, an increase in ALT and diminished albumin, alkaline phosphatase, glucose levels, and relative weight of the heart." (PMID 38794204, 2024). "Hypoalbuminemia is defined as serum albumin less than 3.5 g/dL, while normal serum albumin is defined as serum albumin of 3.5 g/dL or greater." (PMID 38817798, 2024). "First, albumin serves as a nutritional indicator, and individuals exhibiting hypoalbuminemia are indicative of suboptimal nutritional health." (PMID 38771840, 2024). "The median PFS for patients with hypoalbuminemia was 2 months, while this was 48 months for those with normal albumin." (PMID 38755213, 2024). "When calculating the anion gap, correcting for low serum albumin is essential, especially when a previous review of cases demonstrated that hypoalbuminemia can be in seen up to a third of cases." (PMID 39114848, 2024). "Four patients with lesion diameters of 3.71 cm, 3.46 cm, 3.26 cm, and 2.63 cm developed postoperative hypoalbuminemia and only needed albumin supplementation." (PMID 39185469, 2024). "Marked hypoalbuminemia (albumin up to 20 g/L) was observed in five patients (8.6%), with the lowest values being 14 g/L." (PMID 38535548, 2024). "Studies have demonstrated a higher incidence of overt HE in cirrhotic patients with hypoalbuminemia, particularly in those with a serum albumin level ≤31.6 g/L." (PMID 39301299, 2024). "Since furosemide binds to albumin for transport to its site of action in the kidneys, hypoalbuminemia can impair its effectiveness, necessitating higher doses to achieve the desired diuretic response." (PMID 39768386, 2024). "The albumin synthesis capacity is further increased in dialysis patients when hypoalbuminemia is present." (PMID 38610630, 2024).
Hypoalbuminemia (continued). "The possible mechanisms of pre-treatment hypoalbuminemia in canine lymphoma have been described as a decrease in albumin production owing to the response to systemic inflammation associated with tumor progression." (PMID 38595652, 2024). "Specifically, inflammation increases capillary permeability and the escape of serum albumin, leading to hypoalbuminemia." (PMID 38178002, 2024). "Assessing albumin and adjusting it, especially for levels below 4 g/dL, is needed in order to avoid an underestimation of hypoalbuminemia." (PMID 39518465, 2024). "The length of hospital stay was eight days for patients with a normal albumin level and 23 days for hypoalbuminemia patients." (PMID 38707022, 2024). "Inflammatory conditions lead to hypoalbuminemia through heightened capillary permeability, resulting in serum albumin leakage and a reduced half-life." (PMID 38406070, 2024). "Among these patients, 15.6% presented with a moderate level of preoperative hypoalbuminemia (serum albumin between 3 and 3.5 g/dl)." (PMID 39544841, 2024). "Moderate to marked hypoalbuminemia was detected in 4 dogs (serum albumin concentration 11–13 g/l, median: 12.2 g/l)." (PMID 39238011, 2024). "Usually, less than 4 g/dL can be considered a decrease in albumin concentration, and some studies have considered that less than 3.5 g/dL as hypoalbuminemia." (PMID 38584962, 2024). "Model 2, incorporating individual albumin and globulins values, showed that dogs with high IFAT titers, hyper beta-globulinemia, hypoalbuminemia, anemia, and high CS were at increased risk of relapse." (PMID 39175031, 2024). "The infection is characterized by a long and systemic OS, with persistently high levels of ROS, oxidized albumin, and hypoalbuminemia, making it impossible to limit COVID-19-induced oxidative damage." (PMID 39125614, 2024). "In our model we have observed all typical signs of NS, i.e. increased cholesterol level (hyperlipidaemia), increased albuminuria and decreased plasma albumin content (hypoalbuminemia)." (PMID 39245782, 2024). "This indicates that RAR not only represents the mathematical combination of RDW and albumin levels but also reflects both hematopoietic dysfunction and hypoalbuminemia." (PMID 38510084, 2024). "Because most plasma Zn is bound to albumin, measured Zn levels will typically be reduced in patients with hypoalbuminemia." (PMID 38450236, 2024). "Among the 222 patients with ALB levels <35 g/L, which is the cut-off value for hypoalbuminemia, 63.5% (141/222) had myopenia." (PMID 39758314, 2024). "Hypoalbuminemia was present among 119 (59.20%) patients whereas 82 (40.80%) patients had normal albumin levels." (PMID 39539863, 2024). "Patients with normal albumin levels had a significantly superior prognosis compared to patients with hypoalbuminemia (OS 28 vs." (PMID 39691271, 2024). "Laboratory examinations identified increased level of plasma lactate (6.50 mmol/l), glomerular hematuria (urinary red blood cells 40-50 cells/HP, deformability 100%) and hypoalbuminemia (serum albumin 18.5 g/l)." (PMID 38250156, 2024). "Hypoalbuminemia (low serum albumin levels) has been found to significantly increase postoperative complications, including infections, delayed wound healing, and prolonged hospital stays." (PMID 39768438, 2024). "Among the 14 cases with hypoalbuminemia, plasma albumin increased to normal levels in four cases, and one case was not reexamined." (PMID 38157053, 2024). "This was consistent with our findings, where both cases with hypoalbuminemia had albumin levels at 3.0 g/dL." (PMID 39457184, 2024). "Although there is controversy surrounding the benefits of exogenous supplementation of serum albumin, based on existing knowledge, we must consider the impact of hypoalbuminemia on inflammatory activity and the risks it portends." (PMID 38420358, 2024). "Dogs with hypoalbuminemia tended to have shorter MST than those with normal serum albumin concentrations." (PMID 38595652, 2024).
Hypoalbuminemia (continued). "The serum ALB concentration was lower than 35 g/L at admission and rebounded transiently with albumin supplementation and then decreased significantly a few days later, indicating recurrent hypoalbuminaemia." (PMID 38519924, 2024). "It included a total of 670 patients, for which around half of them had a normal albumin level (i.e., equal to or greater than 35 g/L), and the other half had hypoalbuminemia (i.e., less than 35 g/L)." (PMID 38707022, 2024). "Hypoalbuminemia leads to inflammation seen in NAE because albumin can sequester fatty acids, thus preventing fatty acid degradation into prostaglandins; additionally, hypoalbuminemia can lead to zinc deficiency since albumin is a prominent carrier of zinc." (PMID 39100037, 2024). "The patients were classified based on hypoalbuminemia (defined as a serum albumin level < 35 g/L) and clinical threshold." (PMID 38420358, 2024). "According to the Common Terminology Criteria for Adverse Events version 5.0 by the US Department of Health and Human Services, hypoalbuminemia is graded in 5 levels, with a normal albumin threshold set at 30 g/L." (PMID 39654230, 2024). "The clinicians should therefore prioritize the monitoring of hypoalbuminemia in aSAH patients, and consider implementing albumin supplementation as a preventive measure against infection." (PMID 38685951, 2024). "Hypoalbuminemia: a disorder characterized by laboratory test results that indicate a low concentration of albumin in the blood." (PMID 39654230, 2024). "51.9% patients were identified as undernourished, experiencing progressive anemia (Hb: 10.9 ± 1.5 g/dL) and hypoalbuminemia (serum albumin: 31.9 ± 8 g/L)." (PMID 39020313, 2024). "The distribution of patients in the normal albumin level group, mild, moderate, and severe hypoalbuminemia groups was as follows: 1115 patients (77.4%), 216 patients (15.0%), 70 patients (4.9%), and 39 patients (2.7%), respectively." (PMID 38420358, 2024). "Patients were divided into two groups based on their albumin levels: normal albumin (≥30 g/dL) and hypoalbuminemia (<30 g/dL)." (PMID 39768386, 2024). "That’s why hypoalbuminemia differently affects the serum bone turnover markers in hemodialysis patients and serum albumin measurement should be considered according to previous study." (PMID 38186360, 2024). "The immunomodulatory role of albumin is widely recognized, as hypoalbuminemia can lead to reduced activation of macrophages and a weaker cell-mediated immune response against cancer cells." (PMID 38997737, 2024). "Hypoalbuminemia incites worse prognosis in dengue patients, supervised albumin transfusion reverts the progress from dengue shock syndrome." (PMID 39741523, 2024). "Dogs with hypoalbuminemia pre-treatment or 4 weeks post-treatment had a significantly shorter ST than those with a normal serum albumin concentration." (PMID 38595652, 2024). "Laboratory tests showed severe hypoalbuminemia (serum albumin: 1.8 g/dL), hypoproteinemia (total protein: 4.5 g/dL), and lymphopenia (absolute lymphocyte count: 800 cells/μL)." (PMID 39233993, 2024). "Low albumin levels observed in positive cases align with literature identifying hypoalbuminemia as a marker of poor prognosis in COVID-19, likely due to its role in immune modulation and vascular integrity maintenance." (PMID 39767161, 2024). "Hypoalbuminemia, or low serum albumin levels, is frequently observed in critically ill patients and has been associated with poor prognosis, increased morbidity, and mortality." (PMID 39768386, 2024). "Existing literature suggests that hypoalbuminemia (commonly defined as a serum albumin concentration ≤ 30 g/L) constitutes a prognostic indicator of adverse outcomes in critically ill patients." (PMID 39101009, 2024). "In this large-scale hospital-based cohort study, we demonstrated significantly worse long-term and in-hospital outcomes of AIS patients with hypoalbuminemia, including low-normal albumin levels, on admission." (PMID 38794724, 2024).
Hypoalbuminemia (continued). "Hypoalbuminemia, defined as a serum albumin concentration of less than 30 g/L, is usually due to increased bleeding or intestinal loss in patients with NEC." (PMID 38413889, 2024). "Recent research has shown that there is a correlation between low levels of albumin in the blood (hypoalbuminemia) and an extended duration of hospitalization in patients with acute exacerbations of chronic obstructive pulmonary disease (COPD)." (PMID 38835754, 2024). "In our series, Vit-D intake had an inverse and significant correlation with albumin (p = 0.016), and there was one patient with both hypoalbuminemia and VDD." (PMID 38732596, 2024). "Hypoalbuminemia (<3.5g/dL) is typically the result of hepatocyte death and impaired albumin synthesis due to chronic liver disease." (PMID 39678198, 2024). "Hypocalcemia often accompanies hypoalbuminemia because the total serum calcium concentration is the sum of ionized calcium and calcium bound to albumin." (PMID 39545043, 2024). "Albumin shows the highest pattern 1 and 4 weeks before onset, and low serum albumin levels (hypoalbuminemia) are a predictor of AKI." (PMID 39039992, 2024). "The high prevalence of hypoalbuminemia, elevated fecal a1-antitrypsin clearance and 99mTc-albumin scintigraphy indicated the presence of GI tract protein loss." (PMID 38297356, 2024). "Future research should focus on the safety and effectiveness of albumin and crystalloid priming strategies in specific populations (such as patients with hypoalbuminemia) or in the MiECC system." (PMID 38229019, 2024). "Over the last 15 years, numerous clinical studies have shown a significant association between low levels of human serum albumin (HSA) and the development of CDI, suggesting that hypoalbuminemia predisposes patients to severe/recurrent episodes." (PMID 39596075, 2024). "Critical illness impacts the rate of albumin synthesis and its degradation and distribution, resulting in hypoalbuminemia." (PMID 39459557, 2024). "Hypoalbuminemia, characterized by an adult serum albumin (Alb) level below 35 g/L, is a prevalent complication in patients with cerebral infarction." (PMID 38779217, 2024). "Hypoalbuminemia, pooled from four studies, increased the odds of developing liver injury when compared to patients with normal levels of blood albumin (OR = 2.10, 95%CI: 1.53–2.88)." (PMID 39502524, 2024). "As for the length of hospital stay, it was eight days for patients with a normal albumin level and 23 days for hypoalbuminemia patients." (PMID 38707022, 2024). "The reduction in albumin production in cancer has been supported by an in-vivo investigation, wherein mice with tumors exhibited hypoalbuminemia, mostly attributed to a decline in the abundance of liver albumin mRNA." (PMID 38169970, 2024). "During cancer cachexia, nutritional status becomes poor, and the synthesis of acute phase proteins increases, resulting in hypoalbuminemia due to reduced albumin synthesis in many patients." (PMID 39583480, 2024). "In inflammatory states, capillary escape and breakdown of albumin increased which can lead to hypoalbuminemia." (PMID 39250466, 2024). "Hypoalbuminemia has previously been reported as a predictive marker of COVID-19 mortality, and COVID-19 patients who received albumin infusions have been shown to have reduced IL-6 and IL-2R concentrations." (PMID 39345212, 2024). "This increased permeability allows plasma proteins, such as albumin, to leak into surrounding tissues, leading to hypoalbuminemia and a decrease in plasma colloid osmotic pressure." (PMID 39876908, 2024). "Since the liver is the largest synthetic reserve for albumin synthesis, hypoalbuminemia has been detected." (PMID 38577321, 2024). "In cancer patients, tumor-related cytokines like tumor necrosis factor-α and interleukin-6 can hinder albumin gene transcription in liver cells, leading to hypoalbuminemia." (PMID 39767217, 2024).
Hypoalbuminemia (continued). "Patients with hypoalbuminemia have a low concentration of albumin in the blood, and albumin is a substance that enhances immunity and resistance, so pneumonia patients with hypoalbuminemia will affect the cure of pneumonia, and even increase the risk of death." (PMID 39811157, 2024). "Previous studies have shown that serum albumin is an independent prognostic factor in CRC, and hypoalbuminemia is associated with poor survival in CRC." (PMID 36600242, 2023). "Although the iCa is usually considered to be approximately 45% of the tCa, because calcium in the blood is bound to albumin, the proportion of the iCa is higher in cows with hypoalbuminemia." (PMID 37885616, 2023). "The only exception was albumin, which is in agreement with the hypoalbuminemia often observed in the context of physiological stress or inflammation." (PMID 36982564, 2023). "This phenomenon is further aggravated by the occurrence of hypoalbuminemia, the presence of which should be considered in our cohort of patients (median albumin concentrations 29 g/L)." (PMID 36978398, 2023). "Albumin is the most abundant plasmatic protein, and hypoalbuminemia is a mortality prognostic factor in elderly people." (PMID 38075229, 2023). "The majority of cats with FIP have hyperglobulinemia or hypoalbuminemia, or both, leading to a low albumin-to-globulin (A:G) ratio." (PMID 37235153, 2023). "Hypoalbuminemia is common among patients with malignancies, and serum albumin level is an important prognostic factor for patients with CRC." (PMID 36793606, 2023). "Elevated IL-6 levels can impair the liver’s ability to synthesize albumin, leading to hypoalbuminemia." (PMID 37512137, 2023). "The mean values of serum albumin and natrium levels were within the normal range between the two groups, although some patients had hypoalbuminemia and hyponatremia." (PMID 37886238, 2023). "Where plasma albumin and other plasma proteins decrease in severe malnutrition, hypoalbuminemia’s etiology is multifactorial and not only related to nutrition." (PMID 38187790, 2023). "Nevertheless, after PSM, the hypoalbuminemia patients with albumin infusions had significant differences in mortality compared to those without albumin infusions (OR:0.52, 95%CI:0.29–0.92, P = 0.023)." (PMID 37277756, 2023). "As albumin is crucial for tissue healing and integrity, we recommend adjustment of that parameter in patients with hypoalbuminemia prior to surgery, through IV infusion of albumin, as the enteral route is already compromised by the achalasia." (PMID 37052709, 2023). "Serum albumin is known as an indicator of host inflammatory status, and hypoalbuminemia indicates a low baseline nutrition status." (PMID 36819679, 2023). "Albumin replacement improves effective blood volume, compensating for hypoalbuminemia, and increasing the intrinsic antioxidant and detoxifying capacity related to this protein." (PMID 36676081, 2023). "Reduced levels of albumin i.e. hypoalbuminemia is commonly seen in hospitalized patients and in a large proportion of critically ill patients." (PMID 36996133, 2023). "Decreased serum albumin levels are common in COVID-19 patients and hypoalbuminemia has been shown to correlate with mortality." (PMID 36788868, 2023). "Most previous studies considered abnormally low albumin levels, namely, hypoalbuminemia, as an indicator of poorer outcomes, including more rapid CKD progression and cardiac events in ESRD." (PMID 36766578, 2023). "This retrospective research explores not only the relationship between albumin and the outcomes of SAP but also the association between albumin infusions and mortality in hypoalbuminemia patients with SAP." (PMID 37277756, 2023). "Hypoalbuminemia (generally defined as serum albumin concentration < 30 g/L) is a very common condition in critically ill patients." (PMID 37218881, 2023).